MTOR (mechanistic target of rapamycin kinase)
Description:
Serine/threonine protein kinase which is a central regulator of cellular metabolism, growth and survival in response to hormones, growth factors, nutrients, energy and stress signals. MTOR directly or indirectly regulates the phosphorylation of at least 800 proteins. Functions as part of 2 structurally and functionally distinct signaling complexes mTORC1 and mTORC2 (mTOR complex 1 and 2). In response to nutrients, growth factors or amino acids, mTORC1 is recruited to the lysosome membrane and promotes protein, lipid and nucleotide synthesis by phosphorylating key regulators of mRNA translation and ribosome synthesis. This includes phosphorylation of EIF4EBP1 and release of its inhibition toward the elongation initiation factor 4E (eiF4E). Moreover, phosphorylates and activates RPS6KB1 and RPS6KB2 that promote protein synthesis by modulating the activity of their downstream targets including ribosomal protein S6, eukaryotic translation initiation factor EIF4B, and the inhibitor of translation initiation PDCD4. Stimulates the pyrimidine biosynthesis pathway, both by acute regulation through RPS6KB1-mediated phosphorylation of the biosynthetic enzyme CAD, and delayed regulation, through transcriptional enhancement of the pentose phosphate pathway which produces 5-phosphoribosyl-1-pyrophosphate (PRPP), an allosteric activator of CAD at a later step in synthesis, this function is dependent on the mTORC1 complex. Regulates ribosome synthesis by activating RNA polymerase III-dependent transcription through phosphorylation and inhibition of MAF1 an RNA polymerase III-repressor. Activates dormant ribosomes by mediating phosphorylation of SERBP1, leading to SERBP1 inactivation and reactivation of translation. In parallel to protein synthesis, also regulates lipid synthesis through SREBF1/SREBP1 and LPIN1. To maintain energy homeostasis mTORC1 may also regulate mitochondrial biogenesis through regulation of PPARGC1A (By similarity). In the same time, mTORC1 inhibits catabolic pathways: negatively regulates autophagy through phosphorylation of ULK1. Under nutrient sufficiency, phosphorylates ULK1 at 'Ser-758', disrupting the interaction with AMPK and preventing activation of ULK1. Also prevents autophagy through phosphorylation of the autophagy inhibitor DAP. Also prevents autophagy by phosphorylating RUBCNL/Pacer under nutrient-rich conditions. Prevents autophagy by mediating phosphorylation of AMBRA1, thereby inhibiting AMBRA1 ability to mediate ubiquitination of ULK1 and interaction between AMBRA1 and PPP2CA. mTORC1 exerts a feedback control on upstream growth factor signaling that includes phosphorylation and activation of GRB10 a INSR-dependent signaling suppressor. Among other potential targets mTORC1 may phosphorylate CLIP1 and regulate microtubules. The mTORC1 complex is inhibited in response to starvation and amino acid depletion. The non-canonical mTORC1 complex, which acts independently of RHEB, specifically mediates phosphorylation of MiT/TFE factors MITF, TFEB and TFE3 in the presence of nutrients, promoting their cytosolic retention and inactivation. Upon starvation or lysosomal stress, inhibition of mTORC1 induces dephosphorylation and nuclear translocation of TFEB and TFE3, promoting their transcription factor activity. The mTORC1 complex regulates pyroptosis in macrophages by promoting GSDMD oligomerization. MTOR phosphorylates RPTOR which in turn inhibits mTORC1 (By similarity). As part of the mTORC2 complex, MTOR transduces signals from growth factors to pathways involved in proliferation, cytoskeletal organization, lipogenesis and anabolic output. In response to growth factors, mTORC2 phosphorylates and activates AGC protein kinase family members, including AKT (AKT1, AKT2 and AKT3), PKC (PRKCA, PRKCB and PRKCE) and SGK1. In contrast to mTORC1, mTORC2 is nutrient-insensitive. mTORC2 plays a critical role in AKT1 activation by mediating phosphorylation of different sites depending on the context, such as 'Thr-450', 'Ser-473', 'Ser-477' or 'Thr-479', facilitating the phosphorylation of the activation loop of AKT1 on 'Thr-308' by PDPK1/PDK1 which is a prerequisite for full activation. mTORC2 also regulates the phosphorylation of SGK1 at 'Ser-422'. mTORC2 may regulate the actin cytoskeleton, through phosphorylation of PRKCA, PXN and activation of the Rho-type guanine nucleotide exchange factors RHOA and RAC1A or RAC1B. The mTORC2 complex also phosphorylates various proteins involved in insulin signaling, such as FBXW8 and IGF2BP1 (By similarity). May also regulate insulin signaling by acting as a tyrosine protein kinase that catalyzes phosphorylation of IGF1R and INSR; additional evidence are however required to confirm this result in vivo. Regulates osteoclastogenesis by adjusting the expression of CEBPB isoforms (By similarity). Plays an important regulatory role in the circadian clock function; regulates period length and rhythm amplitude of the suprachiasmatic nucleus (SCN) and liver clocks (By similarity).
Synonyms: FRAP; FRAP1; FRAP2; RAFT1; RAPT1; FLJ44809; SKS
Tractability: Small molecule: an approved drug acts on it; a structure with a bound ligand is known; a high-quality ligand is known; it belongs to a druggable protein family. Antibody: UniProt places it where antibodies can reach, with high confidence; its Gene Ontology location is reachable by antibodies, with high confidence. PROTAC: UniProt records ubiquitination sites on it; ubiquitination databases record sites on it; its protein half-life has been measured; a small molecule that binds it is known.
Target class: Enzyme; Kinase; Atypical protein kinase PIKK family; Protein Kinase; Atypical protein kinase FRAP subfamily; Atypical protein kinase group
Chemical probes: APITOLISIB (high quality), AZD-8055 (high quality), EVEROLIMUS (high quality), GDC-0349, PD080680, PD080684, PD080704, PD080708, PD080714, PD080722, PD080736, PD080738, PD080817, PD080837, PD080839, PD080843, PD080859, PD080883, PD080905, PD080909, and 208 more
Safety:
Unwanted effects reported when the protein is acted on. In parentheses: how it was acted on, where the effect was seen, and who reports it.
heart disease (cardiovascular system; source: Force et al. (2011))
Gene: Protein-coding gene on chromosome 1 (11,106,531 to 11,262,556, reverse strand). Ensembl gene ENSG00000198793.
Subcellular location: Lysosome membrane; Endoplasmic reticulum membrane; Golgi apparatus membrane; Cell membrane; Mitochondrion outer membrane; Cytoplasm; Nucleus; Nucleus, PML body; Microsome membrane; Cytoplasmic vesicle, phagosome
Subcellular location (Human Protein Atlas): Cytosol; Golgi apparatus
Pathways (Reactome):
Signal Transduction: Energy dependent regulation of mTOR by LKB1-AMPK; MTOR signalling; PIP3 activates AKT signaling; Regulation of PTEN gene transcription; VEGFR2 mediated vascular permeability; mTORC1-mediated signalling
Cellular responses to stimuli: Amino acids regulate mTORC1; HSF1-dependent transactivation; High laminar flow shear stress activates signaling by PIEZO1 and PECAM1:CDH5:KDR in endothelial cells
Disease: Constitutive Signaling by AKT1 E17K in Cancer; Dengue virus modulates apoptosis
Autophagy: Macroautophagy
Immune System: CD28 dependent PI3K/Akt signaling
Gene Ontology:
Molecular function: identical protein binding; inositol hexakisphosphate binding; phosphoprotein binding; protein binding; protein kinase activity; protein serine kinase activity; protein serine/threonine kinase activity; protein tyrosine kinase activity; ribosome binding; RNA polymerase III type 1 promoter sequence-specific DNA binding; RNA polymerase III type 2 promoter sequence-specific DNA binding; RNA polymerase III type 3 promoter sequence-specific DNA binding; TFIIIC-class transcription factor complex binding; kinase activity; non-membrane spanning protein tyrosine kinase activity; protein-containing complex binding; transmembrane transporter binding
Biological process: cellular response to amino acid starvation; cellular response to amino acid stimulus; cellular response to insulin stimulus; cellular response to L-leucine; cellular response to leucine starvation; cellular response to methionine; cellular response to nutrient; cellular response to nutrient levels; cellular response to starvation; negative regulation of autophagy; negative regulation of lysosome organization; negative regulation of macroautophagy; negative regulation of protein localization to nucleus; phosphatidylinositol 3-kinase/protein kinase B signal transduction; positive regulation of epithelial to mesenchymal transition; positive regulation of keratinocyte migration; positive regulation of lipid biosynthetic process; positive regulation of protein kinase activity; positive regulation of SCF-dependent proteasomal ubiquitin-dependent catabolic process; positive regulation of transcription by RNA polymerase III; positive regulation of transcription of nucleolar large rRNA by RNA polymerase I; positive regulation of translation; positive regulation of translational initiation; positive regulation of ubiquitin-dependent protein catabolic process; positive regulation of wound healing, spreading of epidermal cells; and 46 more
Cellular component: cytoplasm; cytosol; endomembrane system; endoplasmic reticulum; endoplasmic reticulum membrane; Golgi apparatus; Golgi membrane; lysosomal membrane; lysosome; membrane; mitochondrial outer membrane; nuclear envelope; phagocytic vesicle; plasma membrane; TORC1 complex; TORC2 complex; nucleoplasm; nucleus; PML body; dendrite
Genetic constraint (gnomAD): Loss-of-function variants: 67 observed, 305.97 expected, observed/expected ratio (o/e) 0.22, 90% interval 0.18 to 0.27. The upper end of that interval is the gene's LOEUF score, 0.27, which puts it in group 1 of 6, group 1 being the genes least tolerant of losing a copy. Missense variants: 1,828 observed, 3,329.9 expected, observed/expected ratio (o/e) 0.55, 90% interval 0.53 to 0.57. Synonymous variants: 1,156 observed, 1,247.9 expected, observed/expected ratio (o/e) 0.93, 90% interval 0.88 to 0.97.
Gene-disease validity (ClinGen):
ClinGen rates the evidence that MTOR causes each of these diseases.
overgrowth syndrome and/or cerebral malformations due to abnormalities in MTOR pathway genes (autosomal dominant): Definitive. A disease caused by mosaic gain-of-function (GoF) of several genes in the MTOR pathway (MTOR, PIK3CA, PIK3R2 and AKT3) are functionally the same despite significant phenotypic variability.
Cancer hallmarks: change of cellular energetics (promotes); proliferative signalling (promotes); escaping programmed cell death (promotes); invasion and metastasis (promotes); angiogenesis (promotes)
Homologues: Orthologues: chimpanzee MTOR (100% identical), macaque MTOR (99% identical), guinea pig MTOR (99% identical), pig MTOR (99% identical), mouse Mtor (99% identical), rabbit MTOR (99% identical), rat Mtor (99% identical), zebrafish mtor (90% identical), dog MTOR (89% identical), tropical clawed frog XB994582 (87% identical), Drosophila melanogaster mTor (54% identical). Paralogues in human: PRKDC (16% identical), ATR (15% identical), ATM (15% identical), SMG1 (13% identical), TRRAP (12% identical).
Diseases named in the same sentence as MTOR in open-access papers:
MTOR is named in the same sentence as 1,461 diseases in open-access papers, as found by Europe PMC text mining. Sharing a sentence is not in itself a finding about the gene and the disease. The quoted sentences say what the papers report.
breast cancer (2,484 papers, 2004 to 2026). A primary or metastatic malignant neoplasm involving the breast. "The oncogenic activation of noncanonical TGF-β pathways i.e., phosphoinositide-3-kinase (PI3K), AKT, and mTOR are mutually associated with enhancing the proliferation of mammary cancer cells." (PMID 39792296, 2025). "Activation of the AKT/mTOR signaling pathway is strongly associated with the clonability and survival potential and metastasis of breast cancer cells." (PMID 41145484, 2025). "Breast cancer with mTOR hyperactivity is often due to PIK3CA mutation which occurs in 20–50% of breast cancers." (PMID 40943615, 2025). "A recent study highlighted the ability of plant metabolites to phosphorylate and activate the AKT/mTOR pathway, which is associated with survival and resistance, while simultaneously inducing apoptosis in breast cancer cells." (PMID 41305000, 2025). "It has been shown that curcumin can significantly inhibit the proliferation of breast cancer cells by suppressing the phosphorylation of PI3K/AKT/mTOR signaling pathway-associated proteins." (PMID 41348684, 2025). "Dysregulation of the PI3K/AKT/mTOR pathway is particularly prevalent in hormone receptor-positive (HR+) breast cancers, where it is associated with endocrine therapy resistance." (PMID 40299687, 2025). "KEGG enrichment analysis further revealed that shikonin suppressed key tumorigenesis-related pathways, including the mTOR signaling pathway and pathways implicated in cancer and breast cancer." (PMID 40949144, 2025). "Substantial evidence indicates that PIK3CA mutations lead to aberrant activation of the PI3K/AKT/mTOR signaling pathway, contributing to endocrine therapy resistance in breast cancer and closely correlating with poor prognosis." (PMID 40535135, 2025). "Comparably, it has been demonstrated that flavonoids and isoflavones extracted from Tephroseris kirilowii and Astragalus membranaceus cause cell death in various breast cancer in humans cell types by obstructing the PI3K/AKT/mTOR pathway." (PMID 40717210, 2025). "Aberrant activation of the PI3K/AKT/mTOR pathway is a hallmark of endocrine resistance in HR+/HER2– advanced breast cancer (BC)." (PMID 40989687, 2025). "In cancer environments, hyperactivation of mTOR signaling is common, promoting tumor growth, mutations, and poor survival outcomes in breast cancer." (PMID 39805002, 2025). "The frequently observed dysregulation of the TSC/mTOR pathway in breast cancers further underscores its association with tumorigenesis." (PMID 40567015, 2025). "CPNE1 is pivotal in controlling cell growth and differentiation by triggering the AKT/mTOR pathway and is associated with various types of cancers, including breast cancer." (PMID 40740483, 2025). "AC682 is a chimeric compound that, given alone or plus CDK4/6is or PI3K/mTOR pathway inhibitors, showed anticancer activity in experimental ER+ breast cancer models, including those with ESR1 mutations." (PMID 40244377, 2025). "For instance, curcumin, which comes from turmeric, blocks the PI3K/Akt/mTOR signaling pathway frequently activated in breast cancer containing PIK3CA mutations." (PMID 39852145, 2025). "Apart from NF-κB, MAPK, PI3K/Akt/mTOR and several other signalling pathways implicated in the maintenance of breast cancer stem cells included Wnt and Notch." (PMID 40176859, 2025). "Another study associated PRKAG3 with the mammalian target of rapamycin (mTOR) pathway and breast cancer risk, particularly among patients with estrogen receptor-negative breast cancer." (PMID 40839607, 2025). "Several studies have indicated that PIK3CA mutations activate the PI3K/AKT/mTOR pathway in breast cancer." (PMID 40142329, 2025). "A case report documented a near-complete response in a patient with metastatic breast cancer harboring a somatic STK11 point mutation following treatment with the mTOR inhibitor everolimus." (PMID 41051525, 2025).
breast cancer (continued). "Our previous study revealed that DEPDC1 was exclusively associated with the PI3K/AKT/mTOR signaling pathway in breast cancer, and key genes involved in the activation of this pathway were enriched in patients with elevated DEPDC1 expression." (PMID 40600015, 2025). "Rapamycin, an mTOR inhibitor, has demonstrated promising efficacy in breast cancer therapy by focusing on critical mechanisms implicated in tumor growth and persistence." (PMID 40361560, 2025). "PI3K, AKT, and dual PI3K/mTOR inhibitors enhance FOXO3 nuclear localisation in breast cancer cells which is implicated in both sensitivity and feedback mediated resistance to pathway inhibition." (PMID 40263319, 2025). "Akt/PI3K/mTOR signaling cascade in breast cancer is intricately linked to other lncRNAs, such as MALAT1 and UCA1." (PMID 39858015, 2025). "The increased phosphorylation of mTOR signaling is in accordance with prior studies that demonstrated metastatic HR+ breast cancer had amplifications and mutations to the AKT pathways." (PMID 39000231, 2024). "One critical pathway implicated in breast cancer progression is the PI3K/AKT/mTOR signaling cascade, which plays a pivotal role in regulating cellular processes such as metabolism, growth, proliferation, apoptosis, and angiogenesis." (PMID 39850811, 2024). "They lead to activation of the PI3K/AKT/mTOR pathway, promoting cell growth, and proliferation, and are associated with poor prognosis in advanced breast cancer." (PMID 39742376, 2024). "The hyperactivation of the PI3K/AKT/mTOR pathway has also been associated with endocrine resistance in ER+ breast cancer." (PMID 38791941, 2024). "In line with our results, recent meta-analyses have shown that the hyperactivation of mTOR is associated with a better prognosis, such as in non-small-cell lung cancer and in luminal breast cancer." (PMID 38673889, 2024). "Resistance to CDK4/6i and ET for HR+ breast cancer is found to be associated with alterations in the PI3K/AKT/mTOR pathway." (PMID 39409880, 2024). "Recently, Rapalink-1, a drug linking rapamycin and the mTOR kinase inhibitor MLN0128, was developed with favorable therapeutic efficacy in breast cancer cells harboring mTOR resistance mutations." (PMID 38421832, 2024). "mTOR, a central regulator of cell growth and survival, is often dysregulated in breast cancer, with overactivation linked to cell proliferation and therapeutic resistance." (PMID 39850811, 2024). "As expected, the PI3K/AKT/mTOR pathway as well as the RAS/RAF/MAPK pathway were associated with HER3 mutations in breast cancer." (PMID 38951909, 2024). "Lastly, phosphorylated ribosomal S6 kinase 1 (pS6K1), a downstream regulator of the mTOR pathway, was recently identified as a biomarker for adipogenesis, and its overexpression was associated with drug resistance and worse prognosis in breast cancer patients." (PMID 39333940, 2024). "Resistance to endocrine therapy in breast cancer is associated with the activation of the phosphatidylinositol 3-kinase (PI3K)–Akt-mammalian target of rapamycin (mTOR) intracellular signaling pathway." (PMID 37173991, 2023). "For instance, resistance to HER2-targeted therapy in breast cancer has been linked to activation of the PI3K/AKT/mTOR pathway." (PMID 37711177, 2023).